INS (insulin)
Diseases named in the same sentence as INS in open-access papers (continued):
Sharing a sentence is not in itself a finding about the gene and the disease.
multiple endocrine neoplasia type 1 (5 papers, 2014 to 2026). An autosomal dominant tumor predisposition syndrome caused by pathogenic variants in the MEN1 gene, characterized by an increased risk of tumors of the parathyroid glands, pituitary gland, and foregut neuroendocrine tumors (most commonly pancreatic islet cells). "Especially in the setting of multiple neuroendocrine tumours, such as in the Multiple Endocrine Neoplasia Type 1 (MEN1) syndrome, expression analysis of glucagon, insulin, gastrin and pancreatic polypeptide allows identification of which one is the tumour responsible for a hormonal syndrome." (PMID 33855635, 2021).
non-proliferative diabetic retinopathy (5 papers, 2014 to 2024). Early stage diabetic retinopathy, characterized by the absence of neovascularisation of the retina. "Proper glucose and insulin homeostasis should be the primary concern for anyone diagnosed with proliferative diabetic retinopathy (PDR) or non-proliferative diabetic retinopathy (NPDR)." (PMID 37637673, 2023).
osteomyelitis (5 papers, 2021 to 2025). An acute or chronic inflammation of the bone and its structures due to infection with pyogenic bacteria. "For the insulin–osteomyelitis pair, only male patients generated a weak signal (ROR 2.00, 95% CI 1.53–2.63, IC025 0.57)." (PMID 36865915, 2023). "Strong signals associated with osteomyelitis were generated for canagliflozin or any drug groups containing canagliflozin, whereas weak signals were generated for insulin–osteomyelitis pairs, and no signal was generated for other hypoglycemic drugs or drug groups excluding canagliflozin and insulin." (PMID 36865915, 2023). "For osteomyelitis associated with empagliflozin, the ROR value is 2.72 (95% CI 1.22–6.06) and the IC025 is −0.19, whereas other SGLT2is as well as other hypoglycemic drugs, except for insulin, did not generate valid ROR values." (PMID 36865915, 2023). "ROR, IC025, and q-ROR tendencies of the canagliflozin–osteomyelitis pair were significantly different from those generated by the insulin–osteomyelitis pair, and there was no positive signal for hypoglycemic drugs paired with osteomyelitis other than canagliflozin and insulin." (PMID 36865915, 2023). "As displayed by the insulin–osteomyelitis pair, only the dataset of male patients could generate a valid ROR and a weak signal of BCPNN; thus, these findings support the hypothesis that male patients might be more likely to develop osteomyelitis." (PMID 36865915, 2023). "However, based on the FAERS data, drug or drug groups excluding canagliflozin and insulin generated no positive signal with osteomyelitis-related AEs." (PMID 36865915, 2023).
ovarian tumor (5 papers, 2020 to 2023). "In this report, we propose a potentially novel mechanism underlying NICTH involving stimulation of the insulin signaling pathway in a 58-year-old woman with a rare ovarian tumor of Müllerian origin that carries a duplication of the AKT2 gene." (PMID 35822150, 2022). "Previous studies have identified that the miR-34c and the miR-320 act as regulatory molecules of insulin-producing in mesenchymal stem cells or cell proliferation in ovarian tumor cells via targeting to MAPK1 or MAP2K1, respectively." (PMID 38174044, 2023). "Incidental finding of an ovarian mass gave rise to the suspicion of an insulin-producing ovarian tumor." (PMID 33868680, 2021).
pancreatic autoimmunity (5 papers, 2016 to 2025). "Some scholars believe that autoimmune pancreatitis caused by high load HBV virus infection leads to autoantibodies against insulin cells and is the critical factor of GDM." (PMID 35899024, 2022). "Monogenic forms of autoimmune diabetes share clinical features with T1D, such as an early onset, the presence of pancreatic autoimmunity, or a favorable response to treatment with exogenous insulin." (PMID 39870583, 2025). "One month later, the patient commenced on prednisolone therapy for the treatment of autoimmune pancreatitis, after which his total insulin dosage increased to a maximum of 52 units/day." (PMID 30895163, 2019). "A honeymoon period has also been observed, and it now seems clear that pancreatic autoimmunity in patients with T1DM does not guarantee an absolute deficiency in insulin production/secretion." (PMID 27992493, 2016).
Paralysis (5 papers, 2008 to 2022). Paralysis of voluntary muscles means loss of contraction due to interruption of one or more motor pathways from the brain to the muscle fibers. "Together, these adaptations foster an unstable systemic metabolism supported by elevated biomarkers for inflammation (C-reactive protein), abnormal lipid profiles, and abnormal glycemic control (glucose, insulin, lactate) in people with paralysis." (PMID 36278750, 2022). "An excessive insulin secretion with the oral glucose tolerance test rationalized that she had experienced frequent attacks of paralysis on high‐carbohydrate diets." (PMID 32104981, 2020). "While it appears logical that postprandial electrically induced muscle contractions may minimize insulin peaks among people with paralysis, there are several reasons why this needs to be scientifically explored." (PMID 36278750, 2022).
polycythemia (5 papers, 2018 to 2022). Abnormally high mass or concentration of red blood cells in the blood, either due to an increase in erythropoiesis or a decrease in plasma volume. "High insulin and glucose result in increased rate of placental metabolism and stimulation of peripheral hematopoietic embryos after birth, accumulation, and neonatal polycythemia." (PMID 30820209, 2018).
pulmonary edema (5 papers, 2010 to 2025). Accumulation of fluid in the lung tissues causing disturbance of the gas exchange that may lead to respiratory failure. "Pulmonary oedema is a rare but possible paradoxical complication following the withdrawal of high-dose insulin euglycemic therapy (HIET)." (PMID 41466811, 2025). "Although high-dose insulin and extracorporeal life support were the interventions supported for the patients with severe CCB, supportive management might be useful in the treatment of noncardiogenic pulmonary edema after amlodipine overdose without refractory hypotension and bradycardia." (PMID 26075111, 2015).
pulmonary TB (5 papers, 2016 to 2024). "The oxidation of glucose produces gluconolactone, an inflammatory marker previously observed in pulmonary TB, when insulin becomes depleted." (PMID 38560518, 2024).
resistant hypertension (5 papers, 2019 to 2025). "It moves identification and handover to earlier and makes them automatic, then relies on existing local protocols for complex pharmacotherapy (for example anticoagulation/antiplatelet management, insulin adjustment, resistant hypertension, steroid cover)." (PMID 41218980, 2025).
retinal (5 papers, 2011 to 2021). "We confirm that cones are highly dependent on insulin signaling for survival in vitro and demonstrate that insulin and the insulin sensitizers rosiglitazone and metformin prevent RD-induced cone loss in vivo, despite the persistence of retinal inflammation." (PMID 33243251, 2020). "In the current study, we used a series of complementary approaches to examine the role of pancreas-derived insulin in the regulation of retinal IR activity." (PMID 33915127, 2021). "We previously demonstrated that intravitreal injection of insulin restores retinal IR activity." (PMID 22046295, 2011). "In this study, we hypothesized that inhibition of high mobility group box 1 (HMGB1) could restore normal insulin signaling in retinal endothelial cells (REC) grown in high glucose, as well as protect the retina against ischemia/reperfusion (I/R)-induced retinal damage." (PMID 28542588, 2017).
retinitis pigmentosa (5 papers, 2015 to 2025). Retinitis pigmentosa (RP) is an inherited retinal dystrophy leading to progressive loss of the photoreceptors and retinal pigment epithelium and resulting in blindness usually after several decades. "In retinitis pigmentosa, where RdCVF levels are extinguished due to the primary loss of rods, systemic administration of insulin improved glucose uptake in cones and delayed their death, despite the absence of RdCVF." (PMID 33243251, 2020). "In retinitis pigmentosa, where cones die secondary to the primary loss of rods and their RdCVF secretion, systemic administration of insulin improves glucose uptake in cones and inhibits their death, despite the absence of RdCVF." (PMID 33243251, 2020). "Insulin depletion in vivo in mice with underlying rod cell degeneration reduces PI3K activity and causes cell death in cone photoreceptors, leading to retinitis pigmentosa." (PMID 25907958, 2015).
Seizure (5 papers, 2021 to 2023). A seizure is an intermittent abnormality of nervous system physiology characterized by a transient occurrence of signs and/or symptoms due to abnormal excessive or synchronous neuronal activity in the brain. "Seizures would especially occur after brisk glucose elevation in predisposed individuals, such as preterm infants who have a decreased ability to suppress endogenous glucose production, immature insulin response to glucose, and limited glycogen and fat stores." (PMID 37048663, 2023). "This retrospective study shows that epileptic seizures in NKH may correspond to a rare and specific neuro-endocrine entity, reversible within 24 hours with rehydration and insulin therapy and not requiring antiepileptic treatment." (PMID 36060985, 2022).
tendinopathy (5 papers, 2014 to 2025). "The upper normoglycemic range has been proposed as a risk factor for degenerative rotator cuff tendon tear (RCT), and insulin resistance has been suggested as a risk factor for tendinopathy." (PMID 38102571, 2023). "Disorders of insulin and thyroid hormones metabolism are related to tendinopathy both in vitro and in vivo, and sex hormones may promote changes in the structure of tendons, thus influencing their response to physical exercise." (PMID 31842921, 2019).
thyroid storm (5 papers, 2010 to 2026). "Third, if the thyroid function tests revealed the diagnosis of thyroid crisis, the physician should start the management with antithyroid drugs, insulin and intravenous fluids." (PMID 35370958, 2022). "This case highlights complex interactions in polydrug ingestions and suggests insulin may provide protection against thyroid storm in mixed overdoses." (PMID 41732503, 2026). "After literary review, we present what we believe to be the first case of thyroid storm and DKA occurring in the same person on multiple occasions with an insulin pump." (PMID 32140319, 2020).
allergic rhinitis (4 papers, 2023 to 2026). Inflammation of the nasal mucous membranes caused by an IgE-mediated response to external allergens. "The different forms of insulin can present different pharmacokinetics when applied nasally to individuals with different demographic backgrounds and medical conditions (e.g., colds and allergic rhinitis)." (PMID 38441832, 2024). "Specifically, the most important interactions were between the following factors: maternal stress and allergic rhinitis, with a mean SHAP value of 0.0070; maternal stress and insulin, with a mean SHAP value of 0.006 and maternal stress with dairy intake, with a mean of 0.006." (PMID 38783062, 2024).
amyloidoma (4 papers, 2020 to 2024). Nodular localized form of amyloidosis with predominantly thoracic localization (pulmonary amyloidosis), considered as secondary protein structure disease in which insoluble protein fibrils accumulate extracellularly. "Due to its rare nature, only a few case reports have been reported, with even fewer describing amyloidoma as distant from the insulin injection site." (PMID 39081432, 2024). "Our results emphasize that the chronic pathological effect of iatrogenic insulin amyloid fibrils comprising amyloidomas should be further investigated." (PMID 35515176, 2020). "The amyloid mass has also been referred to as an “amyloidoma” and “insulin ball”." (PMID 35563343, 2022).
aortic stenosis (4 papers, 2017 to 2024). Aortic valve stenosis is a aortic valve disease caused by the incomplete opening of the aortic valve. "If measures increasing insulin sensitivity decrease the risk of aortic stenosis warrants further studies." (PMID 39593205, 2024). "Insulin signaling pathway activity rose in all aortic stenosis groups from the sixth week onwards, increasing over time with the exception of AoSHF which showed a drop in insulin level." (PMID 37047174, 2023).
aortic valve calcification (4 papers, 2016 to 2024). "ADIPO-IR, as a unique predictor of IR in adipose tissue, may reflect the antilipolytic effect of insulin in adipose tissue, as well as suggesting progression of aortic valve calcification and adverse cardiovascular features." (PMID 39474255, 2024). "In a Finnish cross-sectional study of an elderly population, fasting insulin was not frelated to aortic valve calcification or AS." (PMID 39593205, 2024).
apical periodontitis (4 papers, 2020 to 2024). "Rats with apical periodontitis exhibit low insulin sensitivity and impaired insulin signaling, which could be rescued by melatonin." (PMID 36498871, 2022).
ataxia telangiectasia (4 papers, 2014 to 2024). Ataxia-telangiectasia is the association of severe combined immunodeficiency (affecting mainly the humoral immune response) with progressive cerebellar ataxia. "Mean incremental AUC insulin was also higher in the ataxia telangiectasia group with a mean difference of 19 640 pmol/l/min (P = 0.03; 95% CI 1997.3, 32,783.6)." (PMID 26606753, 2016). "The 2‐h insulin concentrations were higher in the ataxia telangiectasia group than in the control group (mean difference=137.1 pmol/l; P = 0.043; 95% CI 4.4, 269.8)." (PMID 26606753, 2016). "Nevertheless, our results show a relative reduction in insulin sensitivity in participants with ataxia telangiectasia when compared with healthy participants." (PMID 26606753, 2016). "Fasting insulin concentrations were 39.7 and 41.4 pmol/l in the ataxia telangiectasia and control groups, respectively (P = 0.87)." (PMID 26606753, 2016). "The Matsuda index, reflecting whole‐body insulin sensitivity, was lower in participants with ataxia telangiectasia (5.96 vs 11.03; P = 0.019) than in control subjects." (PMID 26606753, 2016). "Both types of patients have increased serum IGF-1 and IGFBP-2 levels, and decreased serum IGFBP-1 levels; while only ataxia-telangiectasia patients have high serum insulin levels." (PMID 26331037, 2014). "Similarly, there was a marked but appropriate increase in insulin concentrations in participants with ataxia telangiectasia after the glucose challenge." (PMID 26606753, 2016).
Bardet-Biedl syndrome (4 papers, 2013 to 2022). A ciliopathy with multisystem involvement. "We found that cells or animals that are deficient in Bardet Biedl Syndrome proteins are unable to respond to insulin." (PMID 26103456, 2015). "Here, we show that Bardet Biedl Syndrome proteins are required for proper action of insulin." (PMID 26103456, 2015).
behavioral disorders (4 papers, 2021 to 2025). "ELA is associated with altered insulin sensitivity and poor behavioral inhibition throughout life, which seems to contribute to the development of metabolic and psychiatric disturbances in the long term." (PMID 34539334, 2021).
benign breast disease (4 papers, 2018 to 2022). "Association of 18-SNP insulin genetic score with volumetric mammographic density in Karma sub-cohort of non-diabetic women with genotyping data, overall and stratified by genotyping array and with additional adjustment for benign breast disease." (PMID 30092829, 2018). "The aim of this study was to investigate the effect of Berberis vulgaris (BV) juice consumption on insulin homeostasis, glycemic profiles of patients with benign breast disease (BBD)." (PMID 29796035, 2018). "Compared with T2D patients receiving other glucose-lowering medication, insulin-treated T2D patients were younger, had a lower BMI, and were more likely to have comorbid conditions and a history of benign breast disease." (PMID 30092829, 2018). "Taken together, our findings suggest that regular BV juice consumption might be effective on controlling insulin-related indices in benign breast disease." (PMID 29796035, 2018). "However, to the best of our knowledge thus far, this is the first study investigated the effect of BV on insulin-related indices in benign breast disease." (PMID 29796035, 2018).
biliary tract cancer (4 papers, 2011 to 2024). "Emerging evidence shows that insulin and incretin-based drugs are associated with altered risk of biliary tract cancer (BTC)." (PMID 35933633, 2022).
binge eating disorder (4 papers, 2019 to 2025). Recurrent episodes of over-eating. "This case report suggests semaglutide as a potential add-on treatment to insulin able to concomitantly improve glucose control, excess body weight and binge eating disorder symptoms." (PMID 40004833, 2025).
bone metabolism disorders (4 papers, 2021 to 2025). "Irisin facilitates the development of brown adipose tissue and enhances energy expenditure, which in turn improves insulin sensitivity and addresses bone metabolism disorders." (PMID 40136413, 2025).
Bradycardia (4 papers, 2011 to 2024). A slower than normal heart rate (in adults, slower than 60 beats per minute). "Insulin administration was likewise associated with a trend toward greater amelioration of propranolol-induced bradycardia." (PMID 21541209, 2011). "Insulin administration produced marked bradycardia and blood pressure changes in anaesthetized dogs." (PMID 36459572, 2023).
brain tumors (4 papers, 2012 to 2023). "methods: Fasting lipids, glucose, insulin, 24-h blood pressure (BP), and body composition were measured in 36 brain tumour survivors (20 AO; 16 childhood-onset (CO)) and 36 age- and gender-matched controls." (PMID 37253232, 2023).
channelopathies (4 papers, 2025 to 2026). "Furthermore, irreversible Piezo2 channelopathy-induced loss of Piezo2–Piezo1 crosstalk is proposed to increase insulin resistance and dysregulate glucose metabolism in ALS." (PMID 41155507, 2025). "Patients with these specific channelopathies can often be transitioned from insulin injections to oral sulfonylureas, which bind to the SUR1 subunit to close the KATP channel and restore endogenous insulin secretion." (PMID 41614934, 2026). "Consequently, the impaired Piezo2–Piezo1 crosstalk resulting from acquired Piezo2 channelopathy may lead to the abrogation of proper Piezo1 modulation, which could, in turn, result in insulin resistance, given that Piezo1 is involved in glucose-induced insulin secretion." (PMID 40137805, 2025).
ciliopathies (4 papers, 2022 to 2025). "Thus, like in other ciliopathy models, ablation of Bbs5 led to aberrant pancreatic morphology, defective insulin signaling, and impaired glucose homeostasis." (PMID 40233116, 2025).
colonic diseases (4 papers, 2017 to 2025). "Metabolites such as butyrate, short-chain fatty acids, and acetate have been reported to improve gut barrier function, suppress the accumulation of insulin-mediated fat in adipose tissue, and also contribute to prevention of colonic diseases in the host." (PMID 33679680, 2021). "Short-chain fatty acids, including acetate and butyrate, have been shown to improve gut barrier function, suppress insulin-mediated fat accumulation in adipose tissue, and protect the host against colonic diseases." (PMID 32075068, 2020). "CIPII is not indicated in cases of patients with high circulating levels of insulin autoantibodies, poor therapy compliance, evidence of psychiatric conditions, gastrointestinal disorders (e.g., colon diseases, peritoneal adhesions), and unsuitability for external pump use in CSII." (PMID 40995084, 2025).